ADAM10 (ADAM metallopeptidase domain 10)
Diseases named in the same sentence as ADAM10 in open-access papers (continued):
Sharing a sentence is not in itself a finding about the gene and the disease.
breast carcinoma (continued). "Co-expression of APP and ADAM10 was found to correlate with unfavorable prognosis and worse survival outcomes for patients with different subtypes of breast cancers." (PMID 36142659, 2022). "Inhibition of ADAM10 was found to block the levels of sAPPα and reduce breast cancer cell growth and migration." (PMID 36142659, 2022). "Recently, ADAM10 has been investigated in breast cancer, particularly the human epidermal growth factor receptor 2 (HER2) enriched subtype." (PMID 33413403, 2021). "Using a series of breast cancer cell lines, we measured the expression of ADAM10 and its substrates by quantitative real-time PCR assay (qRT-PCR) and western blot analysis." (PMID 33413403, 2021). "We performed immunohistochemical staining for ADAM10 in clinical breast cancer tissues in 94 patients receiving NACT." (PMID 33413403, 2021). "High levels of ADAM10 mRNA were correlated with a poor prognosis in the basal subtype of breast cancer, and knockdown of ADAM10 expression decreased migration in TNBC cell lines." (PMID 33413403, 2021). "In fact, some ADAM10 inhibitors were tested in clinical trials including HER2 + breast cancer, but ultimately failed and discontinued due to their ambiguous value." (PMID 33413403, 2021). "Afterwards we examined the clinical value of pre-NACT ADAM10 expression in the 94 breast cancer cases using univariate and multivariate analyses." (PMID 33413403, 2021). "Recently, it has been reported that ADAM10 also contributes to PDL1 cleavage in breast cancer cells." (PMID 32269567, 2020). "Our studies also reveal that miR-891a-5p impeded breast cancer cells proliferation and migration through downregulation of ADAM10 expression, further signifying that miR-891a-5p is a valuable target for breast cancer therapy." (PMID 32328182, 2020). "The expansion of importance in breast cancer emphasizes the examination of ADAM10 cleavage of APP in other cancers." (PMID 32265938, 2020). "In the literature, ADAM10 inhibitors have been used in metastatic breast cancer xenografts, while two clinical trials with Aderbasib in breast cancers have been terminated as the development of this compound has been suspended." (PMID 32668783, 2020). "In HER2+ breast cancer cells, inhibiting or knocking down ADAM10 was similarly shown to enhance Trastuzumab treatment efficacy 32-34." (PMID 32284760, 2020). "TIMP knockout induces CAF-like phenotype in fibroblasts; exosomes derived from TIMPless fibroblasts are rich in ADAM10; exosome delivered ADAM10 promotes cell motility and activates Notch1 and RhoA signaling in breast cancer cells." (PMID 32957712, 2020). "The effects of ionizing radiations on upregulation of ADAM10 expression levels was also shown in a mouse model of breast cancer." (PMID 32269567, 2020). "In this report, we present evidences that ADAM10 is highly expressed in HR-positive breast cancer tissue and silencing ADAM10 can significantly inhibit the proliferation and migration of HR-positive breast cancer cells." (PMID 32328182, 2020). "Further studies are needed to confirm this mechanism in breast cancer as well as to examine the additive effects of ADAM10 inhibitors in combination with monoclonal anti-HER2 therapies, but the cleavage product HER2-ECD shows promise as a prognostic biomarker." (PMID 32265938, 2020). "For example, ADAM10 is a major sheddase of the Her2 ECD in Her2-over-expressing breast cancer cells." (PMID 28915606, 2017). "A disintegrin and metalloproteinase 10 (ADAM10), has been proved to be upregulated in various cancers and involved in cancer progression and metastasis, such as pancreatic cancer, breast cancer, lung cancer and hepatocellular carcinoma." (PMID 27259866, 2016). "Higher ADAM10 levels correlated with poorer relapse-free survival (p≤0.01) in a cohort of HER2 positive breast cancer patients." (PMID 24952873, 2014). "ADAM10 expression was assessed in HER2 positive breast cancer cell lines and xenograft mice treated with trastuzumab." (PMID 24952873, 2014).
breast carcinoma (continued). "Trastuzumab monotherapy upregulated ADAM10 (p≤0.05); and higher pre-treatment ADAM10 levels correlated with decreased clinical response (p≤0.05) at day 21 in HER2 positive breast cancer patients undergoing a trastuzumab treatment window study." (PMID 24952873, 2014). "Trastuzumab treatment increased ADAM10 levels in HER2 positive breast cancer cells (p≤0.001 in BT474; p≤0.01 in SKBR3) and in vivo (p≤0.0001) compared to control, correlating with a decrease in PKB phosphorylation." (PMID 24952873, 2014). "ADAM10 inhibition or knockdown enhanced trastuzumab response in naïve and trastuzumab resistant breast cancer cells." (PMID 24952873, 2014). "To assess the potential prognostic value of ADAM10 levels, we stained a set of consecutive tumor microarrays from a cohort of HER2 positive breast cancer patients for basal ADAM10 expression." (PMID 24952873, 2014). "We therefore proceeded to assess the effect of an ADAM10 inhibitor (ADAM10i) in HER2 positive breast cancer cells." (PMID 24952873, 2014). "We identify ADAM10 as a sheddase capable of releasing the GPNMB/OA ectodomain from the surface of breast cancer cells, which induces endothelial cell migration." (PMID 20711474, 2010). "Given the growing interest in GPNMB/OA targeted agents in breast cancer, our observations that ADAM10 functions as a sheddase for GPNMB/OA have potentially important therapeutic implications." (PMID 20711474, 2010). "Together, these data indicate that ADAM10 is able to release the GPNMB/OA ectodomain from the surface of breast cancer cells." (PMID 20711474, 2010). "Gutwein and colleagues have reported that in the AR breast cancer cell line, L1 cleavage by ADAM10 can be detected to occur both in minute vesicles termed exosomes and at the cell surface to be released into the culture medium." (PMID 20840789, 2010). "We believe L1 promotes breast cancer progression by its upregulated expression and coincident proteolysis by ADAM10 to release the soluble L1ED, which then exerts its autocrine/paracrine stimulatory effect." (PMID 20840789, 2010). "GPNMB/OA is constitutively shed from breast cancer cells in an ADAM10-dependent manner and the shed GPNMB/OA ECD is capable of inducing endothelial cell migration in vitro." (PMID 20711474, 2010). "Also, ADAM10 knockdown by siRNA in MDA-MB-231 breast cancer cells induces apoptosis and reduces the IC50 value of the anticancer drugs paclitaxel and adriamycin (ADR)." (PMID 40214422, 2025). "Consistent with this, ADAM9 and ADAM10 are overexpressed in breast cancer." (PMID 40214422, 2025). "Small molecules, such as AD, and CD and m62A (both analogs of AD), may regulate ADAM10 expression, thus the expression regulation of ADAM10 in various cancer cells, mainly in lung cancer or breast cancer, was further investigated." (PMID 39211038, 2024). "ADAM10 is also likely involved in breast cancer progression." (PMID 38191648, 2024). "The objective of our study was to investigate whether HER receptor activation occurs in response to trastuzumab treatment mediated by ADAM10/17 ligand-release in HER2-low breast cancer cells." (PMID 38600326, 2024). "The active ADAM10 form marks cancer stem-like cells in breast cancer." (PMID 36922678, 2023). "ADAM10 is likely to be involved in breast cancer progression, especially in the basal subtype." (PMID 35379165, 2022). "GPNMB cleavage by ADAM10 was previously demonstrated in breast cancer cells." (PMID 35280996, 2022). "In HER2 + breast cancer, ADAM10 cleaves and sheds HER2 fragment p95HER2." (PMID 33413403, 2021). "Recently, ADAM-10 has been studied in breast cancer, especially in the human epidermal growth factor receptor 2 (HER2)-enriched subtype, and is considered a major sheddase of the HER2 receptor ectodomain, which contributes to HER receptor activation and induction of anticancer drug resistance." (PMID 34502547, 2021).
breast carcinoma (continued). "However, the studies on the roles of ADAM10 in breast cancer have only focused on the HER2 positive type rather than on the triple-negative type." (PMID 33413403, 2021). "Furthermore, our data showed that high ADAM10 expression is an independent predictor of poor 5-year overall survival in breast cancer patients." (PMID 33413403, 2021). "The expression of ADAM10 on CD9-positive exosomes likely may be important in developing the luminal subtype of breast cancer." (PMID 33773551, 2021). "Three exosomal membrane/surface proteins, glucose transporter 1 (GLUT-1), glypican 1 (GPC-1), and disintegrin and metalloproteinase domain-containing protein 10 (ADAM10), were identified as potential breast cancer biomarkers and validated with Western blotting and high-resolution flow cytometry." (PMID 32782317, 2020). "Interestingly, high expression levels of ADAM10 were found in breast cancer tissues as compared to the adjacent normal breast tissues." (PMID 32328182, 2020). "Interestingly, recent studies have reported an association between upregulation of ADAM10 and ADAM17 and acquired resistance to trastuzumab and lapatinib in patients with HER2-positive breast cancer." (PMID 30458861, 2018). "However, two recent papers reported on the correlation of ADAM10 with survival in HER2-positive breast cancer, and NRG-1b-HER3-HER2 signaling was shown to promote trans-endothelial migration of breast cancer cell lines." (PMID 26863569, 2016). "The role of ADAM10 overexpression was reported in several malignancies such as gastric, prostate, and liver although its clinical significance in breast cancer is unknown." (PMID 24952873, 2014). "Our study indicated that ADAM10 is a potential therapeutic target for HER2 positive breast cancers." (PMID 24952873, 2014). "Here we report the first study showing the role of ADAM10 in HER2 positive breast cancer." (PMID 24952873, 2014). "Moreover, in a cohort of HER2 positive breast cancer patients, higher basal ADAM10 expressions were correlated with poorer relapse-free survival." (PMID 24952873, 2014). "In view of our data showing the activities of both ADAM10 and ADAM17 in response to trastuzumab, we would support further studies to be done to assess the efficacy of ADAM10/17 inhibitor as a novel therapy to overcome trastuzumab resistance for HER2 positive breast cancer patients." (PMID 24952873, 2014). "Having determined that GPNMB/OA is constitutively shed in an ADAM10-dependent manner in our breast cancer model systems, we next investigated whether this shed GPNMB/OA ECD possessed angiogenic properties." (PMID 20711474, 2010). "Similarly, miR-365 expression is low, whereas ADAM10 expression is upregulated in triple-negative breast cancer cells compared to normal breast cancer cells, and ADAM10 has been identified as a direct target of miR-365 in these as well as in colorectal cancer and hepatocellular carcinoma cells." (PMID 36293469, 2022). "In addition, APP cleavage by ADAM10 was shown to have an oncogenic role in breast cancer." (PMID 36142659, 2022). "We speculate that ADAM10 is correlated with chemotherapeutic effects in breast cancer." (PMID 33413403, 2021). "Based on the qPCR results in the RPPH1 function cell models, we may infer that RPPH1 promoted breast cancer cell proliferation and cell cycle progression through down-regulation of micro-RNA 122 and influence the expression of ADAM10, PKM2, NOD2 and IGF1R genes." (PMID 29200969, 2017). "This approach may be of particular interest for breast cancers that critically depend on the generation of ErbB-family growth factors via ADAM10 or ADAM17 not only in terms of cell migration and metastasis but also in terms of cell proliferation and tumor growth." (PMID 28260841, 2017). "Paclitaxel-resistant breast cancer cell lines had increased EZH2, ADAM10, ADAM17, and ICOSL expression, suggesting high sICOSL-release ability." (PMID 40708008, 2025).
breast carcinoma (continued). "In further analysis, it was demonstrated that ADAM10 inhibits apoptosis and confers chemoresistance in MDA-MB-231 breast cancer cells via upregulation of CD44 and PrPc proteins." (PMID 40214422, 2025). "Inhibition of ADAM10 by INCB8765 was reported to improve trastuzumab response against BT-474 and SK-BR-3 breast cancer cells." (PMID 40214422, 2025). "Using a published protocol, we developed a panel of breast cancer PDOs with varying HER2 and ER/PR expression in order to test the effects of different anti-HER2 treatments and/or a ADAM10/17 inhibitor." (PMID 38600326, 2024). "Among them, three exosomal membrane/surface proteins, glucose transporter 1 (GLUT-1), glypican 1 (GPC-1), disintegrin, and metalloproteinase domain-containing protein 10 (ADAM10), were identified as potential breast cancer biomarkers." (PMID 37893211, 2023). "Several inhibitors targeting ADAM10 are available, with GI254023X and Aderbasib (INCB7839) as the most advanced examples, the latter tested in a phase II study on breast cancer and currently studied in children with glioblastoma (NCT01254136, NCT04295759)." (PMID 37422628, 2023). "One study investigated the potential roles of ADAM10 on TNBC cells and the effects of combining ADAM10 expression and NACT to improve the OS in breast cancer patients." (PMID 35163586, 2022). "For example, ADAM10 secreted by CAF increased the expression of ALDH, a biomarker of breast cancer stem cells, which promotes cancer cell proliferation, motility, and survival in breast cancer by regulating the downstream of Notch signaling." (PMID 35743249, 2022). "The breast CAFs derived-exosomes, which contained highly expressed ADAM metallopeptidase domain 10 (ADAM10), promoted cell motility by activating RhoA signaling in breast cancer cells." (PMID 34852849, 2021). "The depletion of MEL-18 promoted trastuzumab resistance by increasing ADAM10/17 mediated ErbB ligand production and receptor heterodimerization in HER2 positive breast cancer patients." (PMID 33413403, 2021). "First, we analyzed the protein expression level of ADAM10 in human mammary epithelial cell line MCF10A and different breast cancer cell lines MCF7, T-47D, SK-BR-3, MDA-MB-231, MDA-MB-468 and BT-549 using the western blot assay." (PMID 33413403, 2021). "Immunohistochemical staining of ADAM10 was performed on the tissues from a core-needle biopsy of the tumor before NACT and a post-NACT radical mastectomy in these two cohorts of breast cancer patients." (PMID 33413403, 2021). "Some established oncogenes are also direct targets of miR-655 in other types of cancers, such as Prrx1 in breast cancer, ZEB1 and TGFBR2 in ESCC, ADAM10 in hepatocellular carcinoma, and PAX6 in retinoblastoma." (PMID 33643926, 2021). "Mechanistic investigation unraveled miR-891a-5p but not miR-383-5p impeded the expression of the downstream target ADAM10 by directly binding to its 3'UTR, leading to the inhibition of breast cancer cells proliferation and migration." (PMID 32328182, 2020). "Besides the downregulation of ADAM10 by miR-655-3p in inhibitory activity on the proliferation, invasion, and metastasis of hepatoma cells 30, our investigations suggest a new insight into the regulation of ADAM10 expression by miR-891a-5p in breast cancer cells." (PMID 32328182, 2020). "Further study confirmed that miR-891a-5p impeded ADAM10 expression by directly binding to its 3'UTR, leading to the inhibition of breast cancer cells proliferation and migration." (PMID 32328182, 2020). "Given the variety of important substrates of ADAM10 and ADAM17 in breast cancer as well as other cancers, this study sheds new light on the potential complications associated with these common xenoestrogens." (PMID 32265938, 2020). "In vitro experiments validate that miR-891a-5p hindered the expression of their shared downstream target ADAM10 by directly binding to its 3'UTR, resulting in the inhibition of breast cancer cells proliferation and migration." (PMID 32328182, 2020).
breast carcinoma (continued). "Whereas reconstruction of wild-type CDH1 in human breast cancer cell line MDA-MB-231 didn’t revert the morphology of the human cells, treating this cells with the ADAM10 specific inhibitor, GI 254023X showed a reduced migration without effecting cell numbers." (PMID 31105876, 2019). "ADAM10 is also involved in EGFR and ERBB2 receptor shedding, thus demonstrating its critical role in breast cancer." (PMID 27888801, 2017). "Interrupting ErbB receptor transactivation by a combined inhibitor of ADAM10 and ADAM17 reduced non-small-lung-cancer-cell formation, subcutaneous tumor growth, and breast cancer and fibroplasia." (PMID 28260841, 2017). "The study also evaluated the influence of the ADAM10, NOTCH1, NOTCH3, HES1, LFNG and PSEN1 genes on breast cancer recurrence." (PMID 27888801, 2017). "Based on the results of previous studies, we chose the miR-122 target genes ADAM10, Bcl-w, VEGFC, PKM2, NOD2, IGF1R and NDRG3 to explore the downstream genes in breast cancer." (PMID 29200969, 2017). "We also observe that Colo678 have high ADAM10 expression, suggested to be involved in acquired resistance to HER2-inhibition in breast cancer models." (PMID 28683746, 2017). "Inhibition of ADAM10 activity or expression resulted in an increase of trastuzumab efficacy, which suggested that ADAM10 and ADAM17 are tractable targets for HER2-positive trastuzumab-resistant breast cancer." (PMID 28442704, 2016). "ADAM10 and ADAM17 have been shown to contribute to the acquired drug resistance of HER2-positive breast cancer in response to trastuzumab." (PMID 28442704, 2016). "The two best studied adamalysins, ADAM10 and ADAM17, have been shown to contribute to the acquired drug resistance of HER2-positive breast cancer in response to trastuzumab." (PMID 28442704, 2016). "ADAM10 is a sheddase that cleaves Her2 (CD340), of which the latter oncogene plays a role in the development and progression of aggressive breast cancers." (PMID 25762645, 2015). "We have shown the role of ADAM10 inhibition and knockdown in naïve and resistant HER2 positive breast cancer cells." (PMID 24952873, 2014). "Inhibition or knockdown of ADAM10 enhanced trastuzumab response in parental cells and reversed acquired trastuzumab resistance in HER2 positive breast cancer cells." (PMID 24952873, 2014). "We propose further validation studies to confirm ADAM10 level as a prognostic and predictive biomarker in HER2 positive breast cancer patients undergoing trastuzumab treatment." (PMID 24952873, 2014). "Our studies implicate a role of ADAM10 in acquired resistance to trastuzumab and establish ADAM10 as a therapeutic target and a potential biomarker for HER2 positive breast cancer patients." (PMID 24952873, 2014). "We showed that the upregulation of ADAM10 levels occurred during trastuzumab treatment and upon acquired resistance in HER2 positive breast cancer cells." (PMID 24952873, 2014). "ADAM10/17 protein levels showed no significant change in the breast cancer tissue after chemotherapy." (PMID 40708008, 2025). "In addition to this, several target proteins that have been shown to interact with TP are mostly highly expressed in breast cancer cells, such as XPB, TAB1, ADAM10, DCTPP1, Erα." (PMID 40444046, 2025). "Paclitaxel also didn’t affect ADAM10/17 and ICOSL expression in breast cancer cell lines in vitro." (PMID 40708008, 2025). "Trop-2 cleavage by ADAM10 is prevalent in various tumor types, such as skin, ovarian, colon, and breast cancer, while not being observed in normal cells." (PMID 38794221, 2024). "We previously reported that ADAM10 and ADAM17 metalloproteases mediate resistance to trastuzumab treatment via shedding of HER ligands and the activation of HER receptors in HER2-positive breast cancer cells." (PMID 38600326, 2024). "They speculated that ADAM10 and/or ADAM17 may be involved in regulating the PD-L1/PD-1 pathway and play an important role in antitumour immunity in breast cancer." (PMID 38069391, 2023).